ENSG00000252096
Gene: Small nucleolar RNA gene on chromosome 20 (4,868,984 to 4,869,118, forward strand). Ensembl gene ENSG00000252096.
Homologues: Orthologues: rat LOC120098359 (41% identical). Paralogues in human: SNORA31B (72% identical), SNORA31 (60% identical).